NCF1 (neutrophil cytosolic factor 1)
Diseases named in the same sentence as NCF1 in open-access papers (continued):
Sharing a sentence is not in itself a finding about the gene and the disease.
lupus (29 papers, 2017 to 2025). "We have previously shown that C57 black mice are susceptible to pristane-induced lupus by an NCF1-associated effect, mediated by hyperactive plasmacytoid dendritic cells (pDCs) by activating type I interferon and STAT1 pathways." (PMID 39939342, 2025). "An important remaining question is why and how the interferon response, and the development of lupus, are triggered in the presence of a low ROS-producing NCF1 variant." (PMID 39939342, 2025). "Variants of Ncf-1 causing a loss of function are associated with increased production of IFNα by plasmacytoid dendritic cells in lupus mice, underlying a key role for ROS in the regulation of cytokine responses." (PMID 41503139, 2025). "Mice with Ncf1 mutation and low ROS develop elevated levels of lupus associated antibodies, IgG and C3 deposition in glomeruli, and heightened expression of IFNg-stimulated genes." (PMID 40227295, 2025). "Further genetic studies in mice, rats, and humans have confirmed that NCF1 mutations promote the development of autoimmune arthritis and lupus by lowering the production of ROS." (PMID 38671946, 2024). "In conclusion, NCF1-dependent ROS deficiency drives spontaneous lupus development in mice carrying Yaa, reflected by autoantibodies against dsDNA and nucleosomes, kidney damage, and involvement of lungs and salivary glands." (PMID 36853827, 2023). "In the current study, by using a set of cell-specific Cre-deleter and transgenic mouse strains, we systematically screened and were able to identify pDCs as the major immune cell type responsible for lupus exacerbation due to NCF1 deficiency." (PMID 36853827, 2023). "Several mechanisms have been proposed for the association between NCF1-derived ROS deficiency and lupus development." (PMID 36853827, 2023). "In a mouse model of pristane-induced lupus, NOX2 deficiency (Ncf1-mutated) aggravated and promoted experimental lupus-like autoimmunity by reducing NETs formation and increasing inflammation." (PMID 36829988, 2023). "These discoveries explain the causative effect of dysfunctional NCF1 in lupus and demonstrate the protective role of pDC-derived ROS in disease development driven by NCF1-dependent ROS deficiency." (PMID 36853827, 2023). "Nevertheless, the key immune cell type(s) mediating NCF1-dependent lupus exacerbation and underlying mechanisms require elucidation." (PMID 36853827, 2023). "Here, we aimed to identify the key immune cell type(s) and cellular mechanisms driving lupus pathogenesis under the condition of NCF1-dependent ROS deficiency." (PMID 36853827, 2023). "Remarkably, two independent reports showed a missense variant in Ncf1 in humans associated with systemic lupus erythematosus (SLE), Sjögren’s syndrome, and RA." (PMID 35052516, 2021). "The rare missense variant p.Arg90His (rs 201802880, gnomAD MAF = 0.007) in NCF1 was reported as a complex-disease susceptibility factor for systemic lupus erythematosus (SLE) and other autoimmune diseases." (PMID 33892719, 2021). "Heterozygosity for the p.Arg90His variant in NCF1 has been associated with susceptibility to systemic lupus erythematosus, rheumatoid arthritis, and Sjögren’s syndrome in adult patients." (PMID 33892719, 2021). "The NCF1-regulated differences in the interferon signaling responses were seen in germ-free mice only after immunization, and they were also obvious after pristane injection, which triggered a more severe lupus-associated response." (PMID 39939342, 2025). "The Th1 response, as well as the Th17 response, regulated by Ncf1 deficiency, may be important reasons for mice to be more susceptibility to autoimmune arthritis or lupus." (PMID 34970267, 2021). "For example, Ncf1 polymorphism is a stronger genetic factor of systemic lupus erythematosus (SLE)." (PMID 33717180, 2021).
lupus (continued). "Because increased NCF1 CN is associated with reduced risk of systemic lupus erythematosus, gene conversion of the derived paralogs could act to maintain redundant, functional sequence variants with an advantageous additive effect." (PMID 34009325, 2021). "Furthermore, we observed CCR2 upregulation on NCF1-deficient pDCs, which may favor their migration and accumulation during lupus." (PMID 36853827, 2023). "NCF1 mutations have also been associated with an increased susceptibility for systemic lupus erythematosus (SLE), Sjögren’s syndrome, and rheumatoid arthritis." (PMID 33903979, 2021). "Considering the importance of the GC response in lupus, we explored the impact of NCF1-mediated ROS burst on GC-B cells." (PMID 39939342, 2025). "Next, we applied PISA‐REX to study the role of NCF1 in a murine model of systemic lupus erythematosus (SLE)." (PMID 39120068, 2024). "To uncover the molecular phenomena by which ROS affects pDC function in NCF1‐dependent development of lupus, we isolated pDCs from the bone marrow‐derived cells of wild type (wt) versus Ncf1‐mutant (Ncf1m1j/m1j) B10.Q mice." (PMID 39120068, 2024). "While the loss of IRF3 solubility in PISA was not statistically significant, we observed increased phosphorylation of IRF3 in dendritic cells from peripheral blood of Ncf1‐mutant mice in the spontaneous lupus model." (PMID 39120068, 2024). "Increased numbers of pDCs, together with their hyperactivation via stimulator of interferon genes (STING)/IFN-α/JAK1/STAT1 signaling, resulted in higher IFN-α levels and ISG expression, explaining the impact of NCF1-derived ROS on lupus severity." (PMID 36853827, 2023). "To investigate the role of NOX2-derived ROS from neutrophils in lupus, we used a mouse strain expressing NCF1 under the control of the human S100A8 promoter, Mrp8-Cre.TN3." (PMID 36853827, 2023). "Low capacity to produce ROS because of mutations in neutrophil cytosolic factor 1 (NCF1/p47phox), a component of NADPH oxidase 2 (NOX2) complex, is strongly associated with systemic lupus erythematosus in both humans and mouse models." (PMID 36853827, 2023). "Here, we show that NCF1-dependent ROS at a physiological level limit development of pDCs in lupus through inhibition of the AKT/mTOR signaling." (PMID 36853827, 2023). "NCF1-dependent ROS specifically restored in these cells protected mice from lupus in both PIL and a Yaa-accelerating spontaneous model." (PMID 36853827, 2023). "Third, NCF1 p.R90H aggravates lupus by acidifying the pH of endosomes/lysosomes and facilitating the persistent activation of TLR signaling." (PMID 35788118, 2022). "After elucidating the regulation of NCF1 p.R90H in pDCs in vitro, we sought to clarify its effect on lupus in vivo." (PMID 35788118, 2022). "As HCQ has been proven to be an effective drug in the NCF1 p.R90H–aggravated lupus mouse model, we proceed to investigate the effect of HCQ on in vitro PBMCs from patients with different genotypes." (PMID 35788118, 2022). "Taken together, depletion of pDCs eliminated the difference in lupus manifestation between WT and KI mice, supporting the critical role of pDCs in the pathogenesis of NCF1 variation." (PMID 35788118, 2022). "Since there were no pDC-specific CRE mice, and it seemed impractical to construct cell-specific SNP mice, it would be a challenge to determine the role of NCF1 p.R90H specifically in pDCs using a lupus model." (PMID 35788118, 2022). "Given that the expression of IFN-I–induced genes was higher in A/A patients, we propose that pDCs are critical for NCF1 p.R90H–driven lupus aggravation in humans." (PMID 35788118, 2022). "Of note, the lupus-susceptibility risk loci PTPRC, NCF1 and ITGAM genes, as well as the IRF8,33–35 emerged as hub network genes, suggesting a pathogenic role during evolution from preclinical to clinical LN." (PMID 35906002, 2022).
lupus (continued). "Subsequently, it was confirmed that Ncf1 is also associated with a variety of chronic inflammatory diseases in both animals but importantly also in humans, such as rheumatoid arthritis and systemic lupus erythematosus (SLE)." (PMID 34970267, 2021). "Here the authors show that a single nucleotide polymorphism in the NCF1 gene, NCF1R90H, known to be associated with systemic lupus erythematosus synergizes with mouse norovirus virus infection to promote interferon and toll-like receptor signaling to cause lupus symptoms in mice." (PMID 39939342, 2025). "Finally, we investigated proteome changes in pDCs isolated from wild‐type versus Ncf1‐mutant mice treated with IFN‐α, to uncover the key molecular events associated with this mutation in lupus." (PMID 39120068, 2024). "By applying REX to a murine model of lupus, we demonstrated that upon IFN‐α stimulation, mutant Ncf1, an important gene with polymorphisms in the etiology of this disease, is strongly modulated at the redox, solubility, and expression levels compared to the wt mice." (PMID 39120068, 2024). "ROS produced by DCs prevent spontaneous development of lupus in Ncf1-mutant mice with Yaa." (PMID 36853827, 2023). "Taken together, low ROS production due to NCF1 deficiency enhances AKT/mTOR-dependent pDC generation and promotes pDC migration via CCR2, which may explain the accumulation of pDCs during lupus." (PMID 36853827, 2023). "Second, although NCF1 has been reported to regulate the function of neutrophils and Tregs, we observed no significant change in the proportion of these cells between WT and KI lupus mice." (PMID 35788118, 2022). "Thus, HCQ proved to be an effective drug for alleviating the lupus symptoms aggravated by NCF1 p.R90H." (PMID 35788118, 2022). "Pharmaceutical application of HCQ alleviates the aggravation of NCF1 p.R90H in the lupus model." (PMID 35788118, 2022). "In this study, we explored the function of NCF1 p.R90H in lupus by using knockin (KI) mice." (PMID 35788118, 2022). "The substitution from arginine (R) to histidine (H) at position 90 in NCF1 protein (NCF1 p.R90H) was verified to parallel with lupus-related symptoms, including altered formation of neutrophil extracellular traps (NETs), a high IFN-I signature, and antiphospholipid syndrome (APS)." (PMID 35788118, 2022). "We found that the NCF1 p.R90H variant facilitated endosomal cleavage and activation of TLR7 and TLR9 in the endosome, thereby boosting the TLR pathway and IFN-I production, which resulted in more serious autoimmune responses and aggravated lupus symptoms." (PMID 35788118, 2022). "Neutrophil degranulation was the most significantly enriched pathway in this signature, whereas gene network analysis revealed that the lupus-susceptibility risk loci NCF2, ITGAM, NCF1, RASGRP1 and FCGR2A33–35 were high-degree hub genes, suggesting their central pathogenic role in LN." (PMID 35906002, 2022). "Interestingly, during the revision of this article, a study was published reporting that NCF1 p.R90H promoted lupus through an enhanced Tfh2 response induced by a defective efferocytosis of macrophages when a pristane-induced lupus model was used." (PMID 35788118, 2022). "Different models will help clarify the multiple roles of NCF1 in lupus." (PMID 35788118, 2022). "In this process, we identified pathways enriched within each signature and found that hub genes correspond to lupus susceptibility risk loci (such as the PTPRC, ITGAM, NCF1 and IRF8 genes), reinforcing their pathogenic role in LN and the progression from preclinical to clinical kidney disease." (PMID 35906002, 2022). "In this study, we investigated the function of NCF1 SNP rs201802880 in the progression of lupus." (PMID 35788118, 2022). "An amino acid replacement in the neutrophil cytosolic factor 1 (NCF1-339/NCF1R90H) leading to lower reactive oxygen species induction has been reported as the major SNP for systemic lupus erythematosus (SLE)." (PMID 39939342, 2025).
lupus (continued). "Thus, we confirmed that NCF1 p.R90H aggravated the lupus progression." (PMID 35788118, 2022). "In addition to NCF1, other hypomorphic NOX2 subunits associated with lupus might also contribute to the ROS change in pDCs, of which SNPs in NCF2 were reported by different groups." (PMID 35788118, 2022). "Genome-wide association studies of systemic lupus erythematosus (SLE) in Chinese and Korean populations demonstrated strong association of single nucleotide polymorphisms (SNPs) located in the GTF2I-NCF1 region, rs73366469 (GTF2I), rs117026326 (GTF2I), rs80346167(GTF2IRD1) and rs201802880 (NCF1)." (PMID 31705128, 2019). "In addition, acidic pH in endosomes caused by defective localization of NCF1 activates TLR signaling in plasmacytoid dendritic cells (pDCs), the principal producer of type I IFNs, leading to increased IFN secretion and thereafter more severe disease in the imiquimod-induced lupus model." (PMID 36853827, 2023). "Experimental evidence from knock-in mice supports this hypothesis, as female mice carrying the NCF1 AA genotype exhibit splenomegaly, increased IFN scores, the development of autoantibodies, and lupus-like kidney disease following pristane injection." (PMID 39917298, 2025). "The R-to-H change in NCF1 led to decreased phospholipid-binding affinity, less endosomal localization, and acidified endosomal pH, followed by increased cleavage of TLR7 and TLR9, resulting in excessive activation of pDCs and aggravated lupus progression." (PMID 35788118, 2022). "Ncf1 and NADPH oxidase 2 complex-derived reactive oxygen species are important regulators of several chronic inflammatory disorders, such as multiple sclerosis, gout, psoriasis and psoriatic arthritis, rheumatoid arthritis, and lupus." (PMID 28201982, 2017). "As the effects of NCF1 have been confirmed in both lymphoid and myeloid cells, we could not conclude that the aggravation of lupus by NCF1 p.R90H was exclusively dependent on its function in pDCs." (PMID 35788118, 2022). "In addition, although NCF1 has been proven to be critical for the proinflammatory function of neutrophils, no significant change in the percentage of neutrophils was observed between WT and KI lupus mice, with or without HCQ treatment." (PMID 35788118, 2022). "Therefore, the homozygous NCF1 p.R90H variant closely correlated with autoimmune responses in patients with SLE, and HCQ may serve as a potential drug for the treatment of NCF1 p.R90H–aggravated lupus." (PMID 35788118, 2022).
autoimmune disease (25 papers, 2006 to 2025). A disorder resulting from loss of function or tissue destruction of an organ or multiple organs, arising from humoral or cellular immune responses of the individual to their own tissue constituents. "In conclusion, this study is the first to demonstrate that the autoimmune disease-causal NCF1 variant is associated with a protective effect against TB infection." (PMID 39917298, 2025). "Given the association of NCF1 rs201802880 with autoimmune diseases, which predominantly affect women, we further explored the genotype-disease relationship by stratifying the analysis by gender." (PMID 39917298, 2025). "The NCF1 rs201802880 A variant, while conferring protection against TB, is associated with an increased susceptibility to various autoimmune disorders, exemplifying evolutionary trade-offs." (PMID 39917298, 2025). "In this study, we investigated the association between the autoimmune disease-causal variant NCF1 rs201802880 A and tuberculosis, a persistent global infectious disease." (PMID 39917298, 2025). "This study demonstrates that the autoimmune disease-causal NCF1 variant is associated with a protective effect against TB infection." (PMID 39917298, 2025). "The positional cloning of single nucleotide polymorphisms (SNPs) of the neutrophil cytosolic factor 1 (Ncf1) gene, advocating that a low oxidative burst drives autoimmune disease, demands an understanding of the underlying molecular causes." (PMID 38671946, 2024). "In conclusion, the identification of the autoimmune disease risk NCF1 His90 variant demonstrates an essential role of NOX2-derived ROS in the development of autoimmune diseases." (PMID 36009308, 2022). "Neutrophil cytosolic factor 1 (NCF1) polymorphisms leading to low production of reactive oxygen species (ROS) are strongly associated with autoimmune diseases." (PMID 36448060, 2022). "Dysregulated autoreactive T cell responses have been observed in mice carrying His90 allele or other ROS-reducing variants, suggesting a role of autoimmune disease risk NCF1 variants in the regulation of T cell homeostasis." (PMID 36009308, 2022). "Association of the NCF1 rs201802880 polymorphism with other three autoimmune diseases was investigated in only one case–control study, where SSc and RA, but not AAV, are reported to be associated with the missense mutation." (PMID 36009308, 2022). "This shows that NCF1-339 is one of the strongest SNPs outside the human leukocyte antigen region that is associated with autoimmune diseases." (PMID 36448060, 2022). "Independent studies confirm a strong association of the non-synonymous SNP NCF1-339 (rs201802880) with multiple autoimmune diseases, such as SLE, CGD, and rheumatoid arthritis." (PMID 36448060, 2022). "The causal relationship between the human and rodent hypoactive NCF1 mutations and various autoimmune disorders suggests an essential role of NOX2-derived ROS in the regulation of development of autoimmune disorders." (PMID 36009308, 2022). "In this work, we aimed to perform a comprehensive meta-analysis of the association of the GTF2I-NCF1 locus with various autoimmune diseases and to provide a systemic review on potential mechanisms underlying the effect of the causal NCF1 risk variants." (PMID 36009308, 2022). "In conclusion, the identification of the association of NCF1 with autoimmune disorders demonstrates that ROS is an essential regulator of immune tolerance and autoimmunity mediated disease manifestations." (PMID 36009308, 2022). "Neutrophil cytosolic factor 1 (Ncf1) is a major genetic factor associated with autoimmune diseases and has been identified as a key player in autoimmune mediated inflammation." (PMID 34970267, 2021). "Variations within three of these genes (JAK2, BACH2, and NCF1) previously have been associated with autoimmune diseases." (PMID 33903979, 2021).